CLDN7 (claudin 7)
Diseases named in the same sentence as CLDN7 in open-access papers (continued):
Sharing a sentence is not in itself a finding about the gene and the disease.
tumor (continued). "Claudin-7 functions through integrins to regulate cell proliferation and maintain epithelial cell attachment, and integrin β1 forms a complex of proteins that regulate cell growth and cell cycle progression, which in turn exerts control over tumor cell proliferation." (PMID 36959784, 2023). "Results: the Kaplan–Meier univariate survival analysis showed a significant correlation between survival and Claudin-7 intensity in the invasive front (p = 0.00), a higher expression being associated with a worse prognosis, while Claudin-7 intensity in the tumor core had no impact on survival." (PMID 35740581, 2022). "In addition to the role of tumor-promoting, Wnt/β-catenin could induce an inflammatory cascade by downregulating Claudin-7 (Cldn-7), which is responsible for TJs barrier integrity." (PMID 36135048, 2022). "Therefore, it can be speculated that FN1 and CLDN7 proteins may mediate tumor progression through the network interaction with LCN2 and MMP9." (PMID 36211450, 2022). "Interestingly, claudin-7 functions both as tumor suppressor and promoter." (PMID 30728783, 2018). "However, in colon cancer, the same claudin-7 was shown to be having tumor suppressor effect." (PMID 30728783, 2018). "A recently study by Thuma and colleagues further reported that nonpalmitoylated CLDN7 is required for the formation of intercellular TJs as a TJ protein, as well as inhibiting the tumor metastasis via cytoskeletal keratin and myosin association with EpC, a cancer-initiating cells marker." (PMID 28055967, 2017). "Out of the 7, we highlighted 3 (Claudin 7, α- and β- catenin) whose mRNA, protein levels and/or localization are similar in cells derived from both normal and organ-confined prostate cancer but their levels and/or localization all alter in cells derived from aggressive metastatic tumours." (PMID 24358122, 2013). "By contrast, studies have shown that claudin-7 may promote tumor progression." (PMID 24009024, 2013). "Since CLDN7, CLDN11 and CD274 correlate with the invasive and metastatic ability of tumours, we further did Wound healing assays and transwell assays." (PMID 38575994, 2024). "Therefore, it is speculated that CLDN7 may have a pro-tumor role in BC pathogenesis." (PMID 39175074, 2024). "By delving deeper into the characterization of GC cells, we identified 6 specific tumour cell subtypes: C0 PSCA+ tumour cells, C1 CLDN7+ tumour cells, C2 UBE2C+ tumour cells, C3 MUC6+ tumour cells, C4 CHGA+ tumour cells and C5 MUC2+ tumour cells." (PMID 38894657, 2024). "The overexpression of CLDN7 promotes proliferation, migration, invasive potential, and tumourigenesis of CRC, while decreased CLDN1 expression was proved to stimulate tumour cell invasion and metastases of PC." (PMID 38201579, 2023). "Although claudin-7 has shown promising results as a prognostic tool in TSCC, further studies are needed to confirm its role and the role of other claudins in the neoplasm." (PMID 37686483, 2023). "In a previous study, we found that claudin 7 is a tumor suppressor in ccRCC, and hypermethylation of its promoter or its downregulation facilitates epithelial-mesenchymal transition (EMT) and tumor progression." (PMID 36479115, 2022). "FN1 and CLDN7 have been investigated as TME factors involved in the epithelial to mesenchymal transition (EMT) and metastasis in different tumor types." (PMID 36211450, 2022). "This expression pattern was significantly correlated with both FN1 and CLDN7 RPPA protein levels in READ, indicating that the LCN2–SLC22A17–MMP9 network is involved in the TME regulation of this tumor." (PMID 36211450, 2022). "In CRC, up-regulation, down-regulation and even deletion of Claudin-7 have been reported, and are an important step in tumorigenesis, invasion, epithelial-to-mesenchymal transition (EMT), metastasis and even tumor suppression." (PMID 35740581, 2022). "CLDN7, PRKCB, EEF2 and TFRC protein levels were all found at higher levels in high LN yield tumours (q = 0.0283)." (PMID 35043009, 2022).
tumor (continued). "CLDN7 decreases in a stage-specific manner in CRC, and its expression can induce mesenchymal to epithelial transition (MET) and suppress tumor formation." (PMID 34571860, 2021). "Cldn7 knock down in CRC stem cells promoted cell proliferation, migration, and globular growth in serum-free medium and the ability to form xenograft tumours; cell apoptosis was inhibited, while the cellular epithelial-mesenchymal transition was also observed." (PMID 34281572, 2021). "Cldn7 knockdown enhanced proliferation, migration, and sphere formation but inhibited apoptosis in HCT116CD133+CD44+ cells in vitro and promoted tumour formation in vivo." (PMID 34281572, 2021). "We evaluated the ability of spherical growth in vitro and tumour formation in vivo to clarify that HCT116CD133+CD44+ cells have TIC properties and analyzed the role of Cldn7 in these properties." (PMID 34281572, 2021). "Further, the serum levels of claudin-7 among patients with colorectal cancer (CRC) was significantly reduced and correlated with high tumor stage and high carcinoembryonic antigen levels." (PMID 31861759, 2019). "CLDN1 and CLDN2 stained positive in 10–50% of tumor cells, while CLDN4 and CLDN7 stained positive in ≥50% of tumor cells." (PMID 25393310, 2014). "Both H. pylori-exposed gastric epithelial cells and the tumor biopsies demonstrated significant up-regulation of five common genes (IL-8, CLDN1, KRT17, CLDN7 and MMP7) and down-regulation of four common genes (GPER, KIAA1324, ADA and SLC9A2)." (PMID 24321518, 2013). "Like CLDN7, DLC1 is has been considered a tumor suppressor gene involved in the regulation of the actin cytoskeleton, cell polarity, inter-cell focal adhesion, cell migration, and apoptosis through negative regulation of Rho signaling pathways." (PMID 22616718, 2012). "In real-time RT-PCR analysis, the gene for claudin-7, CLDN7, was found to be upregulated in all the tumor tissue samples studied." (PMID 21789222, 2011). "In all murine tumors examined here, claudin 7 was localized to the perimembrane region, as illustrated by a section of the TM4 tumor." (PMID 15743505, 2005). "CLDN7 downregulation potentiates EMT and tumor progression in ccRCC." (PMID 40687428, 2025). "Although claudin-7 levels were different between genders, tumor stage, grade, and gender had no impact on the protein." (PMID 38188015, 2023). "This decrease in survival occurred independently of Claudin-7 intensity in the tumor core, which had no impact on survival." (PMID 35740581, 2022). "Recently, Claudin-7 has been reported to be also involved in non-tight junction-related functions such as inflammation initiation and in different tumor development steps." (PMID 35740581, 2022). "However, the matched recurrent tumor samples did exhibit a strong positive correlation between CD44 and both CLDN4 and CLDN7 (Pearson correlation, R= 0.58, p= 0.002 and R= 0.61, p= 0.01, respectively)." (PMID 33828978, 2021). "Considering each claudin separately, we found claudin-7 significantly decrease in patients that relapse to distant organs compared to the abdominal recurrence (claudin-7 FC = 0.61, p = 0.016), regardless of the initial tumor stage." (PMID 32850397, 2020). "Genes other than CLDN1, CLDN3, CLDN4, CLDN7, and ZO1 may also be coordinately regulated by DOCK1 and may contribute to tumor growth, but this remains to be investigated." (PMID 31717460, 2019). "Consistent with the murine data, CLDN7 staining was greater in primary tumours than micro-metastases while FSP1 staining was greater in micro-metastases compared to gross metastases and primary tumours." (PMID 27628423, 2016). "TTK, MCM2, CLDN7 and TSPAN13 promote tumor cell proliferation and their overexpression could stimulate drug resistance." (PMID 26515599, 2015).
tumor (continued). "DGCR5 isoform-1 could promote ccRCC cell proliferation, migration, and invasion, which is, at least partially, through sponging the tumor-suppressive miR-211-5p to regulate the expression of EMT key component Snail protein as well as its downstream targets, E-cadherin and CLDN7." (PMID 34322486, 2021). "Simultaneously, expression of TJ markers in tumor and normal squamous epithelial tissues revealed from both semiq-RTPCR and qPCR significant (p < 0.001) down regulation of ZO-1 (3.7-fold), CLDN-1 (2.9-fold), CLDN-7 (3.8-fold), OCLN (1.6-fold) and E-cadherin (2.3-fold) transcripts." (PMID 34316331, 2021). "This study using 3-D cultures showed that the CLDN7 expression is dependent on the microenvironment of the tissue, thus observations of CLDN7 in the homogeneous population of TE cell lines may not reflect the outcome of tumor-microenvironment interaction." (PMID 29719615, 2018). "The EpCAM-claudin-7 complex rather than EpCAM itself was reported to promote in vivo tumor growth." (PMID 24009024, 2013). "However, the authors failed to observe any significant relationships between CLDN7 expression and the clinicopathological features of OC, suggesting that the downregulation of CLDN7 may lead to tumour progression and subsequent metastatic events." (PMID 38201579, 2023). "However, Claudin-7 expression regarding the proportion and intensity was not correlated with age, sex, T stage, N stage, grading, tumor location, venous invasion, lympho-vascular invasion, perineural invasion, growth pattern, tumor deposits and tumor budding (p > 0.05)." (PMID 35740581, 2022). "Finally, neither CLDN4 nor CLDN7 expression was significantly associated with survival of patients with TNBC, which contradicts the previously reported association between CLDN4 expression and BC tumor recurrence." (PMID 25393310, 2014). "The antitumour efficacy of bispecific antibodies plus talazoparib was not improved in the tumours that were insensitive to EGFR blockade, corresponding to the high expression of VIM and FN1 genes and relatively low expression of CDH1 and CLDN7 genes." (PMID 37441599, 2023). "Cancer-initiating cell-tumor exosomes (CIC-TEX) reprogram non-CIC into malignant tumors, and claudin-7, a biomarker for CIC, was recovered in gastrointestinal TEX." (PMID 36959784, 2023). "Analysis of all tumor samples showed a significant negative regression coefficient for CYP1B1 and CLDN7 expression values, consistent with our cell-based experiments." (PMID 36077068, 2022). "CLDN7, rather than CLDN1, showed higher expression in both undifferentiated tumor tissue and the poorly differentiated CNE2 cells, compared with differentiated tissue and the highly differentiated CNE1 cells." (PMID 28055967, 2017). "We showed in this study that knockdown CLDN7 non-selectively with SiRNA on NPC cells triggered down regulation of both palmitoylated and non-palmitoylated CLDN7, as well as a clear reduction of tumor cells metastasis." (PMID 28055967, 2017). "Claudin 7 is expressed on CD4 T-lymphocytes, and downregulated in tumor progression, but not previously identified in glia." (PMID 18088439, 2007).
cancer (74 papers, 2006 to 2025). A tumor composed of atypical neoplastic, often pleomorphic cells that invade other tissues. "Claudin-7 (Cldn-7) is a member of the tight junction (TJs) family and is strongly associated with cancer and inflammation." (PMID 37834263, 2023). "Zeb1 expression in cancer cells was associated inversely with membranous claudin 7 expression (p = 0.010), while relatively strong cytoplasmic claudin 7 expression was associated with increased cytoplasmic Sip1 expression (p = 0.0012)." (PMID 29482498, 2018). "Combined with the immunohistochemical staining data above, CLDN7 demonstrated that the expression in poorly differentiated carcinoma was significantly higher, suggesting a close association with the differentiation of NPC tissue and cells." (PMID 28055967, 2017). "The loss of CLDN7 contributes to a more mesenchymal, stem-like cancer cell phenotype." (PMID 40687428, 2025). "Furthermore, it was also postulated that downregulated expression of claudin-7 is associated with an increased risk of cancer recurrence and poor prognosis." (PMID 34822542, 2021). "The association between CLDN7 and cancer prognosis varied from diverse cancers." (PMID 31998788, 2020). "Reduced expression of claudin-7 is associated with poor patient outcome in several cancers." (PMID 24009024, 2013). "Loss of claudin-7 was correlated with dedifferentiation in several different cancers." (PMID 21789222, 2011). "Increasing evidence shows that the abnormal expression of CLDN7 leads to the destruction of tight junctions between cells, the loss of cell contact inhibition, and abnormal proliferation, which is closely related to the occurrence and development of various malignant tumors." (PMID 38124743, 2023). "In the next step, a comparison analysis using the cancer genome atlas (TCGA) PCa datasets confirmed elevated CLDN7, COL8A1, and ITGA10 mRNA expression in PCa tissue samples." (PMID 38017134, 2024). "Specifically, our results showed an upregulation of Cldn7, Krt7, Axl, Tnc, Itgav, Itgb3, and Vcam1 in EpCAMhigh and EpCAMlow cancer cells relative to levels in full epithelial cancer cells." (PMID 39075581, 2024). "From this, one can reason that at least 65.7% of CRC samples had CLDN7 expression within at least two thirds of the cancer cells." (PMID 38540693, 2024). "We observed that CLDN3, CLDN4, and CLDN7 transcripts were up-regulated in most of the dysplastic or cancer cells, although these genes were also expressed in some of the intestinal cell lineages." (PMID 37196797, 2023). "Altogether, it indicates that the expression of CLDN5, CLDN11, CLDN2, CLDN7, and CLDN12 is associated with regulating the key cancer-associated pathways in the COAD and GSEA datasets." (PMID 37799140, 2023). "Claudin-7 CLDN7 is a known membrane protein that has been shown to be involved in several signaling pathways that promote some cancers, but its role in SACC is still unclear." (PMID 37159817, 2023). "Altered expression of Cldn7 is observed in various cancer types, yet the exact role of Cldn7 in cancer progression is still unclear." (PMID 35832741, 2022). "Several claudins have been found to interact or form complexes with integrins (with such complexes mainly involving claudin-7 and integrin β1) to mediate cancer cell migration through activation of FAK, cytoskeleton reorganization and ECM alteration." (PMID 34354941, 2021).
cancer (continued). "Another very important claudin associated with the pathogenesis of oral cancer appears to be claudin-7, which has been reported to be downregulated in most cases of this type of cancer." (PMID 34822542, 2021). "Among the genes affected by RRBP1, UBE2C, SHC1, and CLDN7 have all been recently identified as highly relevant targets in other cancers." (PMID 34445467, 2021). "When binding with EpCAM, claudin-7 promotes cancer progression, while when binding with integrin β1, claudin-7 maintains cell-matrix adhesion and suppresses the growth and movement of cancer cells." (PMID 34354941, 2021). "The four genes selected through our process which are dysregulated along with CLDN1 and CLDN7 (PIK3CA, SLC6A6, ASAP1, and TMEM-43) are implicated in a variety of cancers." (PMID 34571860, 2021). "We also detected enrichment for transcripts encoding fibroblast-specific protein 1 (FSP1/S100a4), keratins Krt7, Krt8, Krt14 and Krt18 and claudins Cldn3, Cldn4 and Cldn7 in this cluster which were also enriched in epithelial/cancer cells." (PMID 32455670, 2020). "There was a significant association between H score and mRNA expression, with Spearman's r = 0.36 (p = 0.014), confirming variable expression of claudin-7 protein in cancer samples." (PMID 32850397, 2020). "Claudins are solely involved in tight junctions and critical for cell‐to‐cell adhesion in epithelial cells, CLDN2 and CLDN7 have been shown to facilitate the adhesion of cancer cells to the ECM, which is important for cancer metastasis." (PMID 33377642, 2020). "Although a subset of CCRCCs, PRCCs, and ROs express Claudin-7, most of these carcinomas demonstrate mild or moderate membranous positive staining." (PMID 31737127, 2019). "Meanwhile, cell adhesion-associated genes, such as MPZL1, PVRL1, and CLDN7, were also elevated by α-TOS exposure, indicating their decreased cancer metastasis ability." (PMID 29435127, 2018). "Because the poor differentiation of cancer is generally considered to be related to high metastasis and low survival rate, therefore we took the next step to investigate the correlation of CLDN7 expression with the invasion of NPC." (PMID 28055967, 2017). "Twenty-five cases (55.5%) showed claudin-7 positivity more than 50% of cancer cells in which 20 cases (44.4%) showed positivity more than 75%." (PMID 27398181, 2016). "The result showed that, CDH1, VEGFA, PTPRF and CLDN7 were up-regulated in six cancer samples, and MMP2 was down-regulated in ten cancer samples, suggested that these genes, especially MMP2, were dysregualted in most UCB samples." (PMID 24622401, 2014). "The promotion of carcinogenesis and metastasis by carcinoma-specific complexes, comprised of EpCAM with CD44 variants and claudin-7, has been demonstrated in several malignancies." (PMID 24727741, 2014). "Claudin-7, a tight junction protein, has been demonstrated to be abnormally regulated in several types of human cancer." (PMID 23946785, 2013). "Claudin-7 is another claudin that is frequently dysregulated in cancer, and several studies have reported its role in cancer." (PMID 24009024, 2013). "For other types of cancer, a number of studies have compared claudin-7 expression in malignant tissue and normal tissue from patients." (PMID 21310043, 2011). "Histologically normal mucosa from cancer patients also displayed an intense claudin-7 reaction that was detected from the transitional zone." (PMID 21310043, 2011). "Claudin-7 has been found downregulated in several cancers including esophageal, head and neck and prostate cancer." (PMID 21789222, 2011). "A 2.7-fold reduction in the claudin-7 mRNA level was found when comparing the biopsies from healthy individuals with the biopsies of carcinomas (p < 0.001)." (PMID 21310043, 2011). "A highly significant 2.7-fold reduction in the claudin-7 mRNA level was found, when comparing the biopsies from healthy individuals with the samples of carcinomas (p < 0.001, Kruskal Wallis and Dunn's Multiple Comparison test)." (PMID 21310043, 2011).